POP4 (POP4 ribonuclease P/MRP subunit)
Description:
Component of ribonuclease P, a ribonucleoprotein complex that generates mature tRNA molecules by cleaving their 5'-ends.
Synonyms: RPP29
Tractability: PROTAC: ubiquitination databases record sites on it; its protein half-life has been measured.
Gene: Protein-coding gene on chromosome 19 (29,606,283 to 29,617,237, forward strand). Ensembl gene ENSG00000105171.
Subcellular location: Nucleus, nucleolus
Subcellular location (Human Protein Atlas): Nucleoli; Nucleoplasm
Pathways (Reactome):
Metabolism of RNA: tRNA processing in the nucleus
Gene Ontology:
Molecular function: protein binding; ribonuclease P activity; ribonuclease P RNA binding; RNA binding
Biological process: tRNA 5'-leader removal; RNA processing; tRNA processing
Cellular component: multimeric ribonuclease P complex; nucleolar ribonuclease P complex; nucleolus; ribonuclease MRP complex; nucleoplasm; nucleus; ribonuclease P complex
Genetic constraint (gnomAD): Loss-of-function variants: 30 observed, 28.26 expected, observed/expected ratio (o/e) 1.06, 90% interval 0.79 to 1.44. The upper end of that interval is the gene's LOEUF score, 1.44, which puts it in group 5 of 6, group 1 being the genes least tolerant of losing a copy. Missense variants: 282 observed, 288.13 expected, observed/expected ratio (o/e) 0.98, 90% interval 0.89 to 1.08. Synonymous variants: 110 observed, 111.34 expected, observed/expected ratio (o/e) 0.99, 90% interval 0.85 to 1.16.
Homologues: Orthologues: chimpanzee POP4 (99% identical), rabbit POP4 (91% identical), pig POP4 (90% identical), guinea pig POP4 (87% identical), dog POP4 (87% identical), rat Pop4 (85% identical), mouse Pop4 (83% identical), tropical clawed frog pop4 (63% identical), zebrafish pop4 (63% identical), Drosophila melanogaster Pop4 (29% identical), macaque POP4 (27% identical), Caenorhabditis elegans popl-4 (20% identical).
Diseases named in the same sentence as POP4 in open-access papers:
POP4 is named in the same sentence as 12 diseases in open-access papers, as found by Europe PMC text mining. Sharing a sentence is not in itself a finding about the gene and the disease. The quoted sentences say what the papers report.
breast carcinoma (2 papers, 2012 to 2017). "Taken together, our results suggest that UQCRFS1, POP4, C19ORF12, CCNE1 and C19ORF2 are overexpressed in primary breast cancers and/or breast cancer cell lines harbouring their amplification, and may constitute potential drivers of this amplicon." (PMID 22433433, 2012). "Silencing of CCNE1, PLEKHF1, POP4, ZNF536 and TSHZ3 expression selectively reduced cell viability in cancer cells harbouring 19q12 gene amplification but had a significantly lower impact on the survival of breast cancer cells lacking amplification of this locus (t-test P < 0.05)." (PMID 22433433, 2012).
breast tumors (1 paper, 2010). "In both ovarian tumor data sets analyzed the minimal mapped region of gain incorporated the same five genes (POP4, PLEKHF1, C19orf12, CCNE1 and C19orf2), with similar overlapping regions detected in endometrial and breast tumors." (PMID 21103391, 2010).
craniopharyngioma (1 paper, 2021). A benign, partly cystic, epithelial tumor of the sellar region, presumably derived from Rathke pouch epithelium. "Furthermore, POP4, a GNG5 coexpressing promoter gene, is highly expressed in prostate cancer cells, while RIMS1, a GNG5 coexpressing suppressor gene, is lowly expressed in craniopharyngioma." (PMID 34098960, 2021).
endometriosis (1 paper, 2021). The growth of functional endometrial tissue in anatomic sites outside the uterine body. "According to the RefFinder tool and the optimal number of reference genes determined using geNorm, EIF2B1 and POP4 were the two most stable genes for MenMSCs from women with and without endometriosis." (PMID 33686153, 2021). "Interestingly, we found the five most stable genes (EIF2B1, POP4, UBC, CASC3, and MRPL19) were not previously measured in endometriosis expression studies." (PMID 33686153, 2021).
meningioma (1 paper, 2011). A generally slow growing tumor attached to the dura mater. "TOST procedure showed statistical equivalence between normal tissue and meningiomas (± δ = ± 1.5) for three reference genes: CASC3 (+0.87), IPO8 (+0.57) and POP4 (+1.36)." (PMID 21806841, 2011). "Eight highest ranked reference genes (CASC3, EIF2B1, IPO8, MRPL19, PGK1, POP4, PPIA, and RPL37A) plus GAPDH and ACTB were then analyzed in 35 meningiomas, arachnoidea, dura mater and normal brain." (PMID 21806841, 2011). "Those three genes were not normally distributed in meningiomas (CASC3 (P-value = 0.002), IPO8 (P-value < 0.0001) and POP4 (P-value = 0.0005)." (PMID 21806841, 2011).
ovarian carcinoma (1 paper, 2012). A malignant neoplasm originating from the surface ovarian epithelium. "Amplicon-dependent expression of CCNE1, together with the genes POP4, PLEKHF1, C19orf12 and C19orf2 that flank CCNE1 on this segment, was linked with primary treatment failure in ovarian cancer, possibly due to rapid repopulation of the tumor after chemotherapy." (PMID 22291905, 2012).
tumor (5 papers, 2012 to 2025). "We also find that we are able to successfully transfer our cancer models to tumour-adjacent tissue when inspecting the top 6 genes explained by CNVs (i.e. LLPH, YEATS4, UQCRFS1, POP4, CNOT2, and CAND1)." (PMID 40041206, 2025). "The CD8+ PBMC cluster of Pop3 and Pop4 and CD4eff PBMC cluster of Pop0 and Pop4 were distinctly different to the other tissue types with lower expression of checkpoint markers (PD-1, ICOS, and CTLA-4), suggesting a less regulated immune tumor environment in the periphery." (PMID 35320356, 2022).
cancer (4 papers, 2012 to 2025). A tumor composed of atypical neoplastic, often pleomorphic cells that invade other tissues. "Expression levels of POP4, PLEKHF1 and CCNE1 were significantly higher in cancer cells harbouring amplification of the genes encoding these proteins than in cancer cells devoid of amplification of these loci (Mann-Whitney U test P < 0.05)." (PMID 22433433, 2012). "Silencing of POP4, PLEKHF1, CCNE1 and TSZH3 selectively reduced cell viability in cancer cells harbouring their amplification." (PMID 22433433, 2012). "Further studies investigating the mechanisms that lead to a survival advantage in cancer cells harbouring amplification and overexpression of PLEKHF1 and POP4 are warranted." (PMID 22433433, 2012). "Akin to chronic viral infection and cancer systems, pop3 (KLRG1-CD62Lhi) exhibits the characteristics of stem-like progenitor CD8 T cells (high Tcf7, Slamf6, and Cxcr5 expression), whereas pop4 (KLRG1+CD62Lhi) closely resembles a transitory subset (elevated Tbx21, low Tcf1, and Tox expression)." (PMID 39975082, 2025). "The 19q12 amplicon may harbour more than a single 'driver', given that expression of POP4, PLEKHF1, CCNE1 and TSZH3 is required for the survival of cancer cells displaying their amplification." (PMID 22433433, 2012). "Consistent with this hypothesis, we observed that cancer cells harbouring 19q12 amplification require the expression of not only CCNE1, but also PLEKHF1, POP4 and TSHZ3 for their survival." (PMID 22433433, 2012).
adenocarcinoma (1 paper, 2025). A common cancer characterized by the presence of malignant glandular cells. "Copy number variants (CNVs) tend to be more prevalent in HAC than in common adenocarcinomas, and CNVs in CCNE1, VSTM2B, PLEKHF1, and POP4 are only present in HAC samples." (PMID 40740864, 2025).
POP4 also shares sentences with these, for which no sentence is quoted: bladder cancer (1 paper); ovarian tumor (1); prostate carcinoma (1).